IL1B (interleukin 1 beta)
Diseases named in the same sentence as IL1B in open-access papers (continued):
Sharing a sentence is not in itself a finding about the gene and the disease.
tuberculosis (continued). "Furthermore, the downregulation of Tnf, Mapk11, C3, Il1a, and Il1b in the tuberculosis and pertussis pathways reduces macrophages' ability to opsonize bacteria, perform phagocytosis, and initiate inflammatory responses." (PMID 40206211, 2025). "Since miR-190a-3p/IL1B showed significant differential expression in the M.tb infection groups, we conducted an ROC curve analysis to further explore the correlation between miR-190a-3p/IL1B and the clinical characteristics of tuberculosis patients." (PMID 40725488, 2025). "Therefore, we predicted central DEGs in the PPI network and noted strong interactions between TNF, IL-6, IL-10, IL-1β, CSF-2, IL-4, CXCL8, IFN-γ, IL-1α, and CXCL1, all of which are strongly associated with tuberculosis." (PMID 37818041, 2023). "In addition, it was confirmed that metformin increased proinflammatory cytokines (TNF-α, IL-1α, IL-1β, IL-6, IL-18, IL-8, and IFN-α) in Mycobacterium tuberculosis (causative agent of tuberculosis)-infected macrophages." (PMID 37700364, 2023). "Monocytes exposed to bacillus Calmette-Guérin (BCG) vaccine against tuberculosis are reprogrammed to trained immunity response via IL-1β- induced epigenetic regulation in promoter regions of TNFA, IL6 and IL1B caused by the increase of H3K4me3 and a decrease in H3K9me3." (PMID 37731322, 2023). "IL-1 family of cytokines, mainly IL-1α and IL-1β, are essential for resistance to tuberculosis." (PMID 36993821, 2023). "Several mechanisms underlying the pathogenic role of type I IFN in tuberculosis have been described, including the induction of IL-10 cytokine expression and negative regulation of IL-12/IFN-γ and IL-1β/PGE2 host-protective responses, consistent with our in situ findings." (PMID 35503263, 2022). "Thus, we exposed macrophages from patients with active tuberculosis to S‐protein and nigericin followed by quantification of IL‐1β in the cell supernatant." (PMID 34133077, 2021). "tuberculosis parallel evolution has perfected a mechanism that simultaneously controls IL-1β and its regulator IFN-β, which ultimately benefits both the host by keeping the infection and associated immune pathology at check, and the pathogen, by ensuring transmission." (PMID 32327653, 2020). "Furthermore, Type I IFN inhibits host immune defense mechanism by negative regulation of IL-1α and IL-1β in tuberculosis." (PMID 31801478, 2019). "In patients with tuberculosis, IL-1β is expressed in excess and at the site of disease." (PMID 29386556, 2018). "As tuberculosis patients were reported to exhibit lower antigen-specific Th17 response, supplementing IL-1β might enhance Th17 response." (PMID 27867382, 2016). "IL1β is a pro-inflammatory cytokine involved in the initial response to tuberculosis." (PMID 26567164, 2015). "To examine whether changes detected at the level of mRNA were also reflected at the protein level, we focused on IL-1β, a cytokine critical for host resistance to M. tb." (PMID 26580078, 2015). "IL-1β was detected in lung sections of tuberculosis patients and in the animal models." (PMID 18798983, 2008). "This was characterized by significantly elevated pro-inflammatory cytokines such as G-CSF, TNF-α, IL-1α, IL-1β, and IL-6, excessive neutrophil infiltration, and reduced pulmonary lymphocyte levels as tuberculosis (TB) progressed." (PMID 39178329, 2024). "IL-1β contributes to the control of bacterial, viral, parasitic, and fungal infections and has been associated with protection against tuberculosis; however, its persistent production in the absence of infection has been associated with chronic immune activation and inflammation." (PMID 37953818, 2023).
tuberculosis (continued). "IL-1β eradicates invading pathogens by activating neutrophils and macrophages; IL-4 inhibits the activation of macrophages and interferes with the clearance of Mtb by Th1 cells, which is an important factor for promoting the occurrence of tuberculosis and the recurrence of chronic infection." (PMID 35425720, 2022). "A larger amount of IL-1β produced ex vivo by M. tuberculosis-stimulated macrophages from individuals with latent TB than from individuals with active TB has been reported." (PMID 34809460, 2021). "In particular, low miR-20b-5p expression and activated NLRP3/caspase-1/IL-1β pathway were observed in a TB mouse model stably infected with M. tuberculosis." (PMID 32987746, 2020). "The increased expression of VDR and IL-1β in persons with previous extrapulmonary TB suggests that even after successful anti-mycobacterial therapy, their macrophages remain “primed” and demonstrate a brisk response after re-stimulation with M. tuberculosis." (PMID 31039752, 2019). "Secretion of TNF-α and IL-1β by Mtb-infected macrophages promotes necrosis, and this deregulation of cell death pathways may favor the release of viable bacilli, thus leading to the progression of tuberculosis." (PMID 24278357, 2013). "While ouabain monotherapy significantly reduced inflammation, the incomplete normalization of NLRP3/IL-1β levels suggests two complementary strategies: Low-dose corticosteroids could augment ouabain’s immunomodulation while minimizing toxicity, as shown in tuberculosis models." (PMID 40895521, 2025). "In an anti-tuberculosis drug-induced liver injury rat model, pyrrolidine dithiocarbamate effectively decreased the serum level of cytokines (TNF-α, IL-1β, and IL-6) by repressing the phosphorylation of JAK2 and STAT3." (PMID 38543164, 2024). "The relative excess of TNF-α and IL-1β, associated with soluble TNF-α receptor secretion imbalance, was also demonstrated by these authors to be related to the pulmonary cavities in individuals with active tuberculosis (TB)." (PMID 37007342, 2023). "Tuberculosis is the main cause of death in silicosis, and many studies have found that cytokines (IFN-γ, IL-1β and TNF-α) that can inhibit the immune escape of tuberculosis are decreased, but some Th2 cytokines are increased in silicosis." (PMID 36587204, 2022). "In a recent report, the genes coding for IL-1β, TNF, IL-6, and JAK2 accounted for four of the seven most influential hub genes in the host response to tuberculosis disease." (PMID 36059986, 2022). "In fact it was previous demonstrated that pretreatment of M. tuberculosis–infected Mø with IFN-γ specifically inhibited the release of IL-1β suggesting that during TB IFN-γ may suppress lung immunopathology induced by dysregulation of IL-1β." (PMID 33841429, 2021). "Although IL-1RA is also expressed during TB, therefore restraining the IL-1β-induced response, the most notable cross-regulatory mechanism in the context of M. tuberculosis infection is possibly the interplay established between IL-1β and type I interferons (IFNs)." (PMID 34809460, 2021). "While it is well known that Th1 immunity controls tuberculosis in mice through key cytokines IL-12, TNF-α and IL1-β, they are variably expressed after BCG vaccination in mice." (PMID 33365029, 2020). "HIV-tuberculosis patients had higher supernatant concentrations of CSF-3, IFN-ɣ, and IL-1-receptor-antagonist (IL-1RA) and lower concentrations of CSF-2, IL-12p40, IL-1β, IL-6, and TNF-α." (PMID 28369200, 2017). "These include cytokines which have proven to be critical in the host response against tuberculosis, including IL-12, TNF-α and IL-1β." (PMID 27050308, 2016). "Since the proinflammatory cytokines, IL-1β, IL-6, and TNF-α, contribute to granulomatous inflammation in tuberculosis and other granulomatous diseases, we also examined their levels in granulomas from the two groups of mice." (PMID 25530957, 2014).
tuberculosis (continued). "In our future studies, we will investigate whether susceptibility to mycobacterial infection, such as tuberculosis and leprosy, is increased in the absence of caspase-1 or IL-1β, as would indicate the importance of the inflammasome in host defense against mycobacterial infection." (PMID 20671924, 2010). "The BALfluid TNF-α, IL1β, and TNF-α receptor levelswere higher in patienst with cavitated tuberculosis, but there wasno such difference in serum levels." (PMID 17497033, 2007). "Thus, key cytokines and chemokines such as IL-1β, IL-6, IL-8, TNF-α and IFN-γ play an important role in the pathogenesis of both COPD and tuberculosis." (PMID 40141021, 2025). "Among PLWH with a history of tuberculosis (TB), a significant negative correlation was observed with IL-1β and IL-10 levels, indicating lower interleukin levels in PLWH with skin disorders and a history of TB." (PMID 40572779, 2025). "Activation of RAGEs leads to increased inflammation due to the production of reactive oxygen species and proinflammatory cytokines, such as IL-1β and IL17, resulting in defective phagocytosis, coupled with an increase in oxidative stress and changes in the distribution of anti-tuberculosis drugs." (PMID 38399727, 2024). "Among the various cytokines, pro-inflammatory cytokines (TNF-α, IL-6, and IL-1β), and Th1 cytokines (IL-12, IFN-γ, and IL-2) are known to confer significant protection against tuberculosis, while anti-inflammatory cytokines (IL-10 and TGF-β) and type-I interferons (IFN-β) confer susceptibility." (PMID 35832818, 2022). "tuberculosis response induced upon vaccination with BCGΔBCG1419c via pro-inflammatory cytokines, such as IL-1β, and/or other cytokines or chemokines not evaluated in this work." (PMID 32194998, 2020). "That a recent human clinical trial found that consumption of milled vegetative parts of S. frutescens in capsules might promote tuberculosis, is consistent with what would be expected if host production of TNF-α and IL-1β was diminished." (PMID 27575007, 2016). "Notably, higher levels of IL-1β and NLRP3 mRNA were observed in monocyte-derived macrophage from active tuberculosis patients as compared with healthy subjects, suggesting the involvement of NLRP3 inflammasome in human response to mycobacterial infection." (PMID 22558425, 2012). "Within tuberculosis patients the BMI and leptin levels were positively correlated and decreased with increasing disease severity, whereas higher concentrations of IL-6, CRP, IL-1β, cortisol, and ghrelin were seen in cases with moderate to severe tuberculosis." (PMID 22022605, 2011). "That report did not examine the role of IL-1β but other work showed it is protective during tuberculosis." (PMID 22241982, 2011). "IFN-γ, IL-1β, TIMP-1, and TIMP-2 could also be prognostic markers of the course of tuberculosis." (PMID 37686061, 2023). "Thus, IFN-γ, IL-1β, TIMP-1, and TIMP-2 could be prognostic markers of the course of tuberculosis, and proteins involved in the regulation of their synthesis could be potential targets in the pharmacotherapy of the disease." (PMID 37686061, 2023). "In another study, also in an Ethiopian cohort of HIV co-infected TB patients, 7 genes (FCGR1A, RAB24, TLR1, TLR4, MMP9, NLRC4, and IL1B) accurately discriminated between active tuberculosis disease and latent infection." (PMID 33692804, 2021). "The difference of macrophage-specific interleukin-1 beta (IL-1b) response between latent tuberculosis infection (LTBI) and active tuberculosis (TB) remains less studied." (PMID 31781307, 2019). "We evaluated macrophage expression of VDR, TLR2, cathelicidin, and TNF-α, and production of IL-1β in HIV-seronegative persons with previous EPTB, previous pulmonary TB, latent M. tuberculosis infection, and uninfected TB contacts." (PMID 31039752, 2019).
tuberculosis (continued). "In unstimulated samples, patients with HIV-tuberculosis had higher percentages of tumor necrosis factor (TNF)-α+ monocytes compared with controls and higher supernatant concentrations of colony-stimulating factor (CSF)-3 and IFN-ɣ, whereas supernatant concentrations of IL-1β and IL-8 were lower." (PMID 28369200, 2017). "However, previous studies have shown that monocyte functionality may be impaired in active tuberculosis, with CD16+CD14+ monocytes refractory to dendritic cell maturation, leading to impaired antigen presentation and decreased secretion of IL-1β and IL-12." (PMID 28369200, 2017). "Th1 cytokines, such as IL-1β, tumor necrosis factor-α, and interferon (IFN)-γ, are instrumental in activation, recruitment, and organization of immune cells at the site of M. tuberculosis infection, which results in TB granuloma formation." (PMID 35092727, 2022). "Tsaoet al. studied bronchoalveolar lavage (BAL) fluid and serum TNF-α, IL1β, and TNF-α receptor levelsin patients with cavitated and noncavitated tuberculosis." (PMID 17497033, 2007). "Neither granulocytic accumulation, accumulation of IL1B or CXCL8 transcripts, nor M. tuberculosis labeling was detected in other TB samples investigated (n = 4)." (PMID 38385142, 2023).
type 1 diabetes (105 papers, 2006 to 2026). "Interferon-gamma (IFN-γ), TNF-α, and IL-1β are closely associated with the development of type I diabetes." (PMID 36386181, 2022). "Inflammasomes are large protein complexes involved in the maturation of IL-1β, a cytokine associated with the pathophysiology of type 1 diabetes (T1D)." (PMID 31453296, 2019). "This clustering of receptors also applies to key cytokines involved in beta cell destruction in type 1 diabetes, such as IL-1β; interestingly the expression of ECM-associated genes (even at low levels) is associated with diminished IL-1β effects." (PMID 29306997, 2018). "IFNγ and IL1β are implicated in late, adaptive immune processes in islets in type 1 diabetes." (PMID 38081640, 2024). "To investigate whether DSG2 supports islet survival, we challenged isolated islets with the cocktail of pro-inflammatory cytokines implicated in the development of type 1 diabetes; namely TNFα, IL-1β, and IFNγ." (PMID 36309486, 2022). "Furthermore, younger diabetics appear to be increasingly affected by high IL-1b levels, which could be related to the cytokine storm associated with the first stage of type 1 diabetes." (PMID 39597886, 2024). "Type 1 diabetes caused a significant increase in the mean fold change in the relative mRNA expression of the renal proinflammatory markers such as nuclear factor-κB NFKβ, tumor necrosis factor (TNFα), interleukin-1β (IL-1β), and interleukin-6 (IL-6) compared with the control group." (PMID 38044936, 2023). "In the KEGG enrichment analysis of Thoroughbred vs. Yili horses, pathways involving LOC111768588 and IL1β were found to be related to type I diabetes mellitus and Th17 cell differentiation, respectively." (PMID 41157169, 2025). "Type 1 diabetes is characterized by elevated levels of pro-inflammatory cytokines, such as IL-6, TNF-α, and IL-1β, typically transient and linked to the acute immune response against the virus." (PMID 39861189, 2025). "In diabetes type 1, pancreatic β-cell apoptosis is induced by NF-κB activation that is mediated via IL-1β." (PMID 40136627, 2025). "Monoclonal cell populations were treated with pro-inflammatory cytokines (IL-1β, IFNγ, and TNFα) to model type 1 diabetes (T1D) in vitro." (PMID 38562689, 2024). "The cytokines interleukin-1β (IL-1β), interferon-γ (IFNγ) and tumor necrosis factor-α (TNFα) are the main mediators of beta-cell death and are commonly used in vitro as a model of type 1 diabetes pathogenesis." (PMID 37113489, 2023). "The monocytes from type 1 diabetes patients exhibited higher IL-1β secretion potential in response to LPS than the monocytes from non-diabetic donors." (PMID 36918798, 2023). "It has been reported in several studies that monocytes from new-onset type 1 diabetes patients have increased IL-1β basal levels and a more pronounced response to LPS stimulation in vitro." (PMID 36918798, 2023). "Children with newly diagnosed type 1 diabetes had elevated levels of granulocyte macrophage-colony stimulating factor (GM-CSF), IL-2, IL-7, IL-8, IL-1β, IL-17F, IL-21, IL-23, IL-10, and IL-27 compared to control children." (PMID 35693790, 2022). "We have also previously demonstrated that IL-1β represents the immunological link between ventricular arrhythmias and type-1 diabetes." (PMID 36341442, 2022). "In Type 1 diabetes, increased TLR-2 and TLR-4 expression was found in T1D patients and associated with increased NF-κB expression and IL-1β release." (PMID 36688057, 2022). "The adverse effects of IL-1β on human beta cells in vitro and in animal models have promoted recent clinical trials in volunteers with recent-onset type 1 diabetes, using strategies involving the systemic blockade of IL-1β or its receptors." (PMID 35268394, 2022). "GSEA analysis indicates that the high expression groups of ALDH2, C5AR1, CFOS, IL1B, TLR2, TRXR1 jointly participate in the pathways of viral myocarditis, VEGF signaling pathway and type I diabetes mellitus associated with MI." (PMID 34799616, 2021).